TERT (telomerase reverse transcriptase)
Diseases named in the same sentence as TERT in open-access papers (continued):
Sharing a sentence is not in itself a finding about the gene and the disease.
Cognitive impairment (4 papers, 2014 to 2025). Abnormal cognition is characterized by deficits in thinking, reasoning, or remembering. "In our recent study, TERT KO in EC was found to trigger telomere‐independent mitochondrial dysfunction, resulting in cell senescence and aging‐associate phenotypes: tissue hypoxia and hypotrophy, cognitive impairment, and muscle endurance loss." (PMID 39932851, 2025). "The authors demonstrated that neurodegenerative symptoms and brain aging were influenced by shorter telomeres, and conversely, that increasing the level of TERT in the brain of mice, and by extension the telomeres, could significantly revert signs of cognitive impairment." (PMID 36399449, 2022). "Besides preventing cognitive impairment and neurodegeneration through its antioxidant and anti-inflammatory properties, resveratrol has been shown to be able to enhance mitochondria biogenesis by acting on its main effectors, including PGC-1α, SIRT1, AMPK, ERRs, TERT, TFAM, NRF-1 and NRF-2." (PMID 36237161, 2023).
dysplastic nevi (4 papers, 2017 to 2025). "TERT promoter mutations, which are present in up to 80% of cutaneous melanomas, have also been observed among dysplastic nevi." (PMID 31861163, 2019). "TERT promoter mutations have been frequently observed in studies of melanoma in situ but they have also been documented in a subset of nevi with high mutational burdens and dysplastic nevi." (PMID 31861163, 2019). "In addition, dysplastic nevi harbor frequent activating mutations of the telomerase reverse transcriptase (TERT) promoter." (PMID 30934534, 2019). "Benign and dysplastic nevi often displayed surprisingly widespread TERT positivity." (PMID 29262649, 2017). "Taken together, these results suggest that gain of non-nucleolar TERT occurs in a few benign nevi, in some dysplastic nevi, but most commonly at the transition to metastasis." (PMID 29262649, 2017).
esophageal squamous cell carcinoma (4 papers, 2013 to 2020). Esophageal squamous cell carcinoma (ESCC) is a type of esophageal carcinoma (EC) that can affect any part of the esophagus, but is usually located in the upper or middle third. "Nevertheless, the role of these TERT-CLPTM1L variants in the etiology of esophageal squamous cell carcinoma (ESCC) remains unknown." (PMID 24386361, 2013).
ganglioglioma (4 papers, 2018 to 2025). A well differentiated, slow growing neuroepithelial neoplasm composed of neoplastic, mature ganglion cells and neoplastic glial cells. "Besides, the prognostic significance of TERT promoter mutation in cases with a methylation score of ganglioglioma is largely unknown." (PMID 36647073, 2023).
Hematuria (4 papers, 2017 to 2025). The presence of blood in the urine. "Ongoing studies have since led to the development of enhanced Cxbladder Detect and Triage assays, in which six DNA single nucleotide polymorphisms from FGFR3 and TERT have been integrated to further improve risk stratification in patients with hematuria." (PMID 39335740, 2024). "The sensitivity of urinary cfDNA analysis (TERT C228T, TERT C250T, and FGFR3 S249C) was 68.9% in pre-TURBT 1, and the specificity was 96.2% using the hematuria group as the control cohort." (PMID 32509577, 2020).
hepatitis B infection (4 papers, 2014 to 2022). "According to one study, the TERT promoter mutation is strongly linked to hepatitis C and hepatitis B infection in HCC." (PMID 36556980, 2022).
ischemia (4 papers, 2018 to 2022). A hypoperfusion of the BLOOD through an organ or tissue caused by a PATHOLOGIC CONSTRICTION or obstruction of its BLOOD VESSELS, or an absence of BLOOD CIRCULATION. "In a mouse model of ALI-induced by intestinal ischemia-reperfusion, Nrf2 expression can inhibit ferroptosis via modulation of telomerase reverse transcriptase (TERT), HO-1, and SLC7A11 levels." (PMID 35813823, 2022). "Various insults including ischemia, amyloid peptide administration, and glutamate or NMDA-induced excitotoxicity, substantially induce the expression of TERT in rodent neurons." (PMID 29867352, 2018). "Although the TERT−/− and the WT counterparts displayed similar cardiac function and structure as shown by echocardiography and ex vivo pre-ischemia cardiac analysis, basal LVP in the TERT−/− I/R hearts from the Ang II treated group exhibited reduced Dev-LVP and RPP, and higher diastolic LVP." (PMID 31001540, 2019).
lymphocytic thyroiditis (4 papers, 2020 to 2023). "Multivariate logistic regression analysis revealed that sex, Hashimoto’s thyroiditis (HT), tumor size, extrathyroidal extension, TERT promoter mutations and NRAS mutation were independent factors of CLNM." (PMID 36817603, 2023). "Circulatory miR-145 was associated with Hashimoto disease (p = 0.030) and TERT mutation (p = 0.004)." (PMID 36077665, 2022). "The authors found that most of the FTAs positive for TERT mRNA expression presented concomitant lymphocytic thyroiditis, as demonstrated long before." (PMID 37568724, 2023).
lymphopenia (4 papers, 2016 to 2021). Reduction in the number of lymphocytes. "Prudence is needed when designing a selective TERT-targeting immunotherapy, as pointed out by our previous data about the treatment of prostate tumor-bearing mice with three cycles of ACT with mouse TERT-specific CD8+ T cells that caused a transient B-cell lymphopenia." (PMID 29152058, 2017). "Furthermore, the rs2853669 A > G polymorphism in the telomerase reverse transcriptase (TERT) promoter, which disrupts an Ets-TCF-binding site and influences certain cancers, was highly prevalent in SLE patients, possibly contributing to lymphopenia." (PMID 33846459, 2021).
Merkel cell carcinoma (4 papers, 2014 to 2017). "Our recent study showed that 100% (10 cases) of SmCC of the urinary bladder carry TERT promoter mutation C228T, yet none of SmCC from all other origins including prostate, lung, cervix, esophagus, and skin (Merkel cell carcinoma) contain the TERT promoter mutations." (PMID 25937998, 2015). "The regulatory mechanism and clinical significance underlying cancer-specific TERT expression have been extensively investigated in various human malignancies, but little is known about these in Merkel cell carcinoma (MCC), an aggressive neuroendocrine skin tumor." (PMID 25301727, 2014). "In small cell carcinoma from other origins, including 5 cases of Merkel cell carcinoma, 2 case from cervix; 1 case from breast; 1 case from GE junction and 2 cases from soft tissue in extremities, no TERT promoter mutation was identified in all of these cases." (PMID 25042800, 2014).
mesothelioma (4 papers, 2014 to 2021). A usually malignant and aggressive neoplasm of the mesothelium which is often associated with exposure to asbestos. "Among them, those harboring telomerase reverse transcriptase (TERT) gains have shown higher prevalence for chromothripsis and this can be linked to mesothelioma with TERT-impairment that present poorer prognosis." (PMID 34249695, 2021). "While TERT can be mutated at its promoter region (>15% of cases present with C228T somatic mutations), the TERT locus (5p15.3) can also be amplified to induce higher TERT levels (around 50% of mesothelioma); however, the TERT promoter mutation is responsible for elevated TERT expression." (PMID 29342862, 2018). "To obtain a suitable experimental system to study the CSF-1R function in mesothelioma cells, we analyzed the expression of CSF-1R and its ligands CSF-1 and IL-34 in a panel of mesothelioma cell lines and an untransformed mesothelial cell line immortalized by h-TERT (LP9)." (PMID 24722292, 2014). "Since we observed increased Rbm8a editing in the mouse model of mesothelioma development, we investigated editing levels in cDNA from three MPM cell lines and three mesothelial cell lines (LP9/TERT-1, SDM104, and SDM85) using Sanger sequencing." (PMID 34944051, 2021).
metastasis (4 papers, 2019 to 2026). The spread or migration of cancer cells from one part of the body (where they first appeared) to another. "Type of tumor, absence of liver metastasis, lack of prior systemic therapy, and presence of TERT mutation were associated with improved responses to ICIs." (PMID 40867302, 2025).
ovarian clear cell cancer (4 papers, 2018 to 2025). An invasive malignant neoplasm that arises from the ovary and is characterized by a predominance of clear and hobnail malignant epithelial cells. "A screening of TERT promoter mutations in gynecological cancers provided evidence that these mutations are selectively observed in ovarian clear cell carcinomas, where they are observed with a 16% frequency." (PMID 29389895, 2018). "For example, ARID1A directly binds to the TERT promoter region and suppresses TERT expression by promoting chromatin condensation in ovarian clear cell carcinoma." (PMID 41049615, 2025).
serous ovarian cancer (4 papers, 2010 to 2022). "We observed a significantly increased risk of serous ovarian cancer associated with a variant in the telomerase reverse transcriptase (TERT) gene." (PMID 20628624, 2010). "SELENBP1 is identified as one of the candidate stromal epithelial cross-talk genes by analyzing common single-nucleotide polymorphisms (SNPs) for their association between the risk of serous ovarian cancer and telomerase reverse transcriptase (TERT), a cancer susceptibility “hot-spot”." (PMID 36386843, 2022). "Low levels of promoter methylation allow an ATRA inhibitory action on TERT expression and cell growth, as observed in the serous ovarian carcinoma cell line OVCAR3." (PMID 31291979, 2019). "The potential antiproliferative and cytotoxic effect of ATRA was investigated in seven serous ovarian carcinoma and one teratocarcinoma cell lines and the results were compared to the methylation status of their TERT promoter." (PMID 31291979, 2019). "In a parallel project, we analyzed neoplastic tissue of serous ovarian carcinoma patients and observed TERT promoter hypomethylation in about one third of cases." (PMID 31291979, 2019). "TERT: rs2853676 was more strongly correlated with serous ovarian cancer, consistent with our findings." (PMID 28233473, 2017). "Although these results are preliminary, ATRA treatment could become a new powerful, personalized therapy in serous ovarian carcinoma patients, but only in those with tumors harboring a hypomethylated TERT promoter." (PMID 31291979, 2019). "Combined discovery and replication analysis: site-specific and combined risk estimates for serous ovarian cancer for TERT rs7726159 among non-Hispanic whites." (PMID 20628624, 2010). "Combined analysis of the discovery and replication sets for this TERT SNP showed an increased risk of serous ovarian cancer among non-Hispanic whites [adj." (PMID 20628624, 2010). "In summary, we have identified an association between TERT rs7726159 and serous ovarian cancer in a large sample of non-Hispanic White women participating in five OCAC case-control studies." (PMID 20628624, 2010). "Our discovery study was reasonably well powered, so the failure to find any associations with SNPs in genes involved in stromal epithelial cross-talk, except in DCN and TERT, suggests that genetic variation in this pathway is not a major determinant of serous ovarian cancer risk." (PMID 20628624, 2010). "The serous ovarian carcinoma cell line OVCAR3, harboring a hypomethylated TERT promoter, was the best and fastest responder." (PMID 31291979, 2019).
small cell lung carcinoma (4 papers, 2020 to 2025). Small cell lung cancer (SCLC) is a highly aggressive malignant neoplasm, accounting for 10-15% of lung cancer cases, characterized byrapid growth, and early metastasis. "Additionally, certain mutations, such as TERT (telomerase reverse transcriptase) mutations, are present in SCBC but are less common in small-cell lung cancer." (PMID 40895775, 2025).
steatosis (4 papers, 2013 to 2025). Increased lipid within the cytoplasm of cells. "Treatment of the cells for 4 h with the ACLY inhibitor BMS or histone acetyltransferase inhibitor garcinol prior to ChIP-qPCR significantly reversed the steatosis-associated elevation in both H4K16ac and ɣH2AX levels at the TERT promoter." (PMID 35739588, 2022). "Most importantly however, mutations in TERT and in TERC, encoding for the RNA primer of TERT, have been associated with a spectrum of familial hepatic liver disease often associated with histological steatosis similar to NAFLD and hepatic iron overload." (PMID 23394097, 2013). "For instance, five variants in or near TM6SF2, PNPLA3, HFE, APOE, and MTARC1 had comparably larger effects on HCC than on hepatic steatosis (p <0.05 by Cochran’s Q test), while HCC-associated variants in HSD17B13, KLF15, and TERT did not significantly associate with steatosis." (PMID 40823170, 2025).
teratoma (4 papers, 2015 to 2024). A non-seminomatous germ cell tumor characterized by the presence of various tissues which correspond to the different germinal layers (endoderm, mesoderm, and ectoderm). "The colonies isolated from sparse cultures of hiPSC-teratoma cells expressed NANOG and OCT3/4 strongly, and telomerase reverse transcriptase (TERT) weakly." (PMID 26069211, 2016). "TERT was not expressed in 52% (n = 10/19) of the adjacent tissues and only in 8% (n = 2/24) of tumour tissues (teratomas)." (PMID 33530592, 2021). "Additionally, the dedifferentiated cells increased the expression of CD90, CD105, CD106, and TERT, were able to achieve trilineage differentiation, and did not originate teratomas after in vivo transplantation." (PMID 38399261, 2024).
Thrombocytopenia (4 papers, 2016 to 2024). A reduction in the number of circulating thrombocytes. "The patient who died had multiple high-risk features (severe thrombocytopenia and elevated fetal hemoglobin) and acquired additional somatic mutations that included JAK3, TERT, KRAS, and CBL, and eventual transformation to AML." (PMID 39123476, 2024).
transitional cell carcinoma (4 papers, 2012 to 2021). A malignant neoplasm arising from the transitional epithelium, usually affecting the urinary bladder, ureter, or renal pelvis. "Studies have shown that the TERT promoter mutation is highly correlated with the prognosis of transitional cell carcinoma and confirmed that the −124 C > T mutation (corresponding to C228T) is associated with high expression of TERT and telomerase activity." (PMID 34094968, 2021). "Unexpectedly, although 95% of both renal pelvic and ureter cancers are transitional cell carcinoma, the former exhibits a high frequency of TERT promoter mutations, which is close to that in BC, whereas the mutation rate in the later is comparable to RCCs." (PMID 24742867, 2014). "The hotspot TERT promoter mutations named C228T and C250T were recently identified as a key genetic event to activate telomerase in different types of cancer including urothelial cell carcinomas]." (PMID 26934125, 2016).
viral hepatitis (4 papers, 2016 to 2025). An acute or chronic inflammation of the liver parenchyma caused by viruses. "Viral hepatitis, a significant risk factor of HCC, mainly modifies genes such as TERT, PDGFR β, and MAPK1." (PMID 40755497, 2025). "Viral hepatitis, a significant risk factor of HCC, mainly alters genes such as TERT, PDGFR β, and MAPK1." (PMID 40964147, 2025).
adrenal tumor (3 papers, 2014 to 2025). "We assessed C228T and C250T TERT mutations by direct Sanger sequencing in tumors of the adrenal gland, and further evaluated potential associations with clinical parameters and telomerase activation." (PMID 24803525, 2014).
bone marrow failure syndrome (3 papers, 2011 to 2025). "Through mutation screening in patients with DC and related bone marrow failure syndromes, we have identified 23 novel mutations in core components of telomerase: 11 in TERC, 8 in TERT and 4 in DKC1." (PMID 21931702, 2011). "Additionally, patients with ITGV-BMFs may have abnormalities in telomere biology, including critically short telomere and germline variants in gene such as TERT or NOP10, which are linked to inherited bone marrow failure syndromes." (PMID 40574285, 2025).
chordoma (3 papers, 2023 to 2025). Chordomas are rare malignant tumors arising from embryonic remnants of the notochord in axial skeleton. "A methylation analysis of six skull base dedifferentiated chordoma cases at a single institution demonstrated consistent epigenetic changes in the TERT promoter, MAGEA11, and UXT." (PMID 38892063, 2024). "Other key mutations of dedifferentiated chordoma from the meta-analysis include CDKN2A/B, IRF2, KIT, PIK3CA, PTEN, RB1, and the TERT promoter." (PMID 38892063, 2024).
chronic kidney disease (3 papers, 2022 to 2025). Impairment of the renal function secondary to chronic kidney damage persisting for three or more months. "TERT gene variants rs2735940 and rs4635969 are correlated with an increased risk of chronic kidney disease, with rs2735940 variant homozygous genotype associated with increased microalbuminuria in chronic kidney disease patients." (PMID 40231186, 2025).
cognitive decline (3 papers, 2016 to 2025). "Taken together, our data suggests that the mTOR signalling pathway impinges on the mitochondrial localisation of TERT protein, which might in turn contribute to the protection of the brain by DR or rapamycin against age-associated mitochondrial ROS increase and cognitive decline." (PMID 27777385, 2016). "Supporting this, overexpression of TERT in AD mouse models preserved neuronal integrity and attenuated cognitive decline through mechanisms not directly linked to telomere length." (PMID 40748434, 2025). "Preclinical rodent studies utilizing an AAV9-mediated TERT gene therapy approach (AAV9-TERT) have demonstrated the potential of TERT, an enzyme vital for telomere maintenance, in mitigating neurodegeneration and age-related pathologies, including cognitive decline." (PMID 39286667, 2024).
COVID-19 (3 papers, 2023 to 2026). A disease caused by infection with severe acute respiratory syndrome coronavirus 2. "This study aims to identify the association of FAM13A, DSP, TOLLIP, TERT, and THSD4 variants with severe COVID-19 and post-COVID-19 condition in a Mexican mestizo population." (PMID 40076669, 2025). "Recent research has pointed out the relationship between the TERT gene and the consistent presence of short telomeres in patients with severe COVID-19 symptoms." (PMID 40076669, 2025). "The well-known variants in recognized genes related to pulmonary function worsening (THSD4 rs872471) and interstitial disorders (FAM13A rs2609255, DSP rs2076295, TERT rs2736100) are related to the severity and mortality of COVID-19 and lung performance in the post-COVID-19 condition." (PMID 40076669, 2025). "In summary, according to our findings, the involvement of DSP, TERT, and THSD4 during the acute phase of COVID-19 is related to the inflammatory process, cell migration, cytokines release, and the adaptive and innate immune responses." (PMID 40076669, 2025). "These biological routes, including those involving the FAM13A, DSP, TOLLIP, TERT, and THSD4 genes, have not been entirely studied in COVID-19 and post-COVID-19 condition." (PMID 40076669, 2025).
cutaneous squamous cell carcinoma (3 papers, 2013 to 2024).